CAMTA1 (calmodulin binding transcription activator 1)
Diseases named in the same sentence as CAMTA1 in open-access papers (continued):
Sharing a sentence is not in itself a finding about the gene and the disease.
cancer (20 papers, 2012 to 2025). A tumor composed of atypical neoplastic, often pleomorphic cells that invade other tissues. "The hub genes ATP6AP2, ACTR1A, SYNM, ZMYND8, CAMTA1, SLC39A3, and DHCR24, are associated with cancer development and progression." (PMID 39757707, 2025). "In western blotting experiments, we found that the CAMTA1 protein level in the cancer tissue of the mice treated with oxaliplatin was higher than that in the untreated group." (PMID 35332122, 2022). "Endothelial cells highly expressing the product of this translocation, which fuses TAZ to the calmodulin-binding transcription activator 1 (CAMTA1), are associated with this cancer, although the oncogenic mechanism of this fusion protein has yet to be elucidated." (PMID 25097728, 2014). "In summary, except for CDKN2A, which is a clear outlier in the dataset under consideration, the changes in the local number of CNVs did not appear to be connected to the pan-cancer genes located in these regions (CAMTA1 and MTOR, MUC4 and TFRC, and NCOR2)." (PMID 31783642, 2019).
adenocarcinoma (1 paper, 2025). A common cancer characterized by the presence of malignant glandular cells. "Immunohistochemically, adenocarcinoma expresses epithelial markers such as CK and EMA, but negative for CD31, CD34 and especially CAMTA1 and TFE3." (PMID 40040722, 2025). "Genetically, CAMTA1 or TFE3-rearrangement is present in EHE, but not in poorly differentiated adenocarcinomas." (PMID 40040722, 2025).
neurodegenerative disease (1 paper, 2019). A disorder of the central nervous system characterized by gradual and progressive loss of neural tissue and neurologic function. "This suggests a central role for both CAMTA1 and DENND4A proteins in driving transcriptional programs underlying neurodegenerative diseases." (PMID 30357366, 2019). "Interestingly, CAMTA1 and DENND4A both have strong links to neurodegenerative disease." (PMID 30357366, 2019). "Unlike CAMTA1 and DENND4a, no direct connection between MIG12 and neurodegenerative disease has previously been described." (PMID 30357366, 2019).
neurological diseases (1 paper, 2022). "Nevertheless, the function of CAMTA1 in neurological diseases is largely unknown." (PMID 36159397, 2022).
CAMTA1 also shares sentences with these, for which no sentence is quoted: sarcoma (7 papers); epithelioid sarcoma (4); vascular sarcoma (4); cerebellar ataxia (3); colon cancer (3); epithelioid hemangioma (3); cardiovascular disease (2); Cerebellar atrophy (2); endometrial stromal sarcomas (2); Ewing sarcoma (2); hemangioendothelioma (2); alveolar soft part sarcoma (1); attention deficit-hyperactivity disorder (1); Autoimmunity (1); autosomal dominant cerebellar ataxia (1); Bartonella infection (1); breast carcinoma (1); clear cell sarcoma (1); colorectal (1); coronary artery disease (1); Down syndrome (1); gastric cancer (1); generalized epilepsy (1); Hydrocephalus (1); inflammatory myofibroblastic tumor (1); leukemia (1); lung carcinoma (1); myasthenia gravis (1); Non-progressive cerebellar ataxia with mental retardation (1); Obesity (1).
A further 10 diseases each share a sentence with CAMTA1 in 1 paper.